IGF1R (insulin like growth factor 1 receptor)
Diseases named in the same sentence as IGF1R in open-access papers (continued):
Sharing a sentence is not in itself a finding about the gene and the disease.
breast cancer (continued). "Next, we evaluated the ability of long-term MK-0646 antibody treatment to inhibit IGF1R expression in breast cancer cells expressing a wild-type or a mutant BRCA1." (PMID 28706506, 2017). "We previously demonstrated the importance of IGF-1R as a major upstream mediator of breast cancer cell EMT and invasion." (PMID 29212236, 2017). "Since OSI-906 is a dual IGF1R/InsR inhibitor and both receptors are potential therapeutic targets in breast cancer it is important to consider the inhibitory contribution of both receptors to OSI-906 effects." (PMID 29207959, 2017). "Analysis of the predictive impact of IGF1R expression among patients with early breast cancer and among breast cancer subtypes revealed that IGF1R levels correlated with good prognostic markers." (PMID 28706506, 2017). "For example, ginsenoside Rp 1 inhibits the insulin-like growth factor 1 receptor (IGF-1R)/Akt pathway in breast cancer cells." (PMID 28845434, 2017). "In this study, the expression of IGF1R, InsR and pIGF1R/InsR was evaluated in tumors from 946 primary breast cancer patients in a prospective cohort." (PMID 28030849, 2017). "A major mechanism of resistance to anti-IGF-1R drugs involves the IR, which is commonly overexpressed in breast cancer and predominantly expressed as the so called ‘fetal isoform’ (IR-A), which is a bona fide receptor for IGF-2 and proinsulin." (PMID 28591735, 2017). "Previously, it was reported that ErbB2 and IGF1R can heterotrimerize with ErbB3 to enhance receptor activation and downstream signaling responses in ErbB2-overexpressing breast cancer cells." (PMID 28947975, 2017). "We also interfered IGF-IR in breast cancer cell lines and the results showed that miR-152 expression level was inhibited by IGF-1R knockdown." (PMID 29162853, 2017). "The CTS results suggest significant breast cancer protection in women with preeclampsia who possess the IGF1R rs2016347 TT genotype, specifically in those with age at first birth under 30 and for subsequent development of HR+ breast cancer." (PMID 28822014, 2017). "DNA damaging agents have a critical role in cancer therapy, so we next investigated the effect of combining IGF-1R inhibition and cisplatin in three breast cancer cell lines MCF-7, ZR-75-1 and MDA-MB-231 using colony formation assays." (PMID 27472395, 2016). "In the case of the insulin-like growth factor (IGF) pathway, the mTOR complex (mTORC1) mediates IGF-1 receptor (IGF-1R)-induced estrogen receptor alpha (ERα) phosphorylation/activation and leads to increased proliferation and growth in breast cancer cells." (PMID 27765027, 2016). "Using the delivery of shRNA vectors into the Mvt1 cell line, we tested the role of the IGF1R in the development of mammary tumors." (PMID 27179633, 2016). "We examined the associations of 22 polymorphisms across five IGF1 pathway genes (IGF1, IGFBP3, IGF1R, IRS1, and PI3KCB) with risk of breast cancer among women of European and East Asian descent." (PMID 27376028, 2016). "The IGF-1R is also considered as a target for vaccine development for primary prevention of murine model of breast cancer." (PMID 28261624, 2016). "Our study demonstrates that p110β can produce resistance to α-specific PI3K inhibition in an IGF1R/p85/IRS-dependent manner in PIK3CA-mutant breast cancer." (PMID 27048245, 2016). "The completion of three recent clinical trials, two of which specifically examined MK-0646 and MK-8669, reinforce the added value of targeting IGF-1R in conjunction with mTOR in advanced hormone receptor-positive breast cancer tumors." (PMID 27765027, 2016). "A phase I/II clinical trial has started recently for patients with ovarian cancer or breast cancer to evaluate the therapeutic benefit of combining BYL719 with the anti-IGF1R antibody AMG479 (ClinicalTrials.gov NCT01708161)." (PMID 27048245, 2016). "We were next interested to investigate the effects of IGF-1R inhibition on the DNA damage response in breast cancer cells." (PMID 27472395, 2016).
breast cancer (continued). "Enrichment analysis of gene sets from 24 mouse models for breast cancer pinpoint to a potential new function for insulin-like growth factor 1 (Igf1r) in the basal epithelium during lactogenesis." (PMID 27808166, 2016). "Recent data in breast cancer cells have shown that BYL719 resistance was conferred by IGF1R/p110β/Akt/mTOR activation." (PMID 27602501, 2016). "Our study demonstrates that the IGF1R/p110β/AKT/mTOR axis confers resistance to BYL719 in PIK3CA mutant breast cancers." (PMID 27048245, 2016). "We have previously shown that the insulin receptor substrate (IRS) adaptor proteins are necessary for linking IGF1R to downstream signaling pathways and the malignant phenotype in breast cancer cells." (PMID 26991655, 2016). "Consistent with its tumor suppressor role, forced expression of BRCA1 in breast cancer cells led to a marked reduction in endogenous IGF1R levels and promoter activity." (PMID 27446805, 2016). "In summary our study provides a mechanistic rationale for the combination of IGF-1R or IGF pathway inhibitor with ATR inhibitors or other DNA damaging agents in breast cancer." (PMID 27472395, 2016). "Recent research shows that PKM2 interacts with P65 and the PKM2/NF-κB/microRNA (miR)-148a/152 feedback loop, which regulates cancer cell growth and angiogenesis in response to insulin-like growth factor 1 receptor (IGF-IR) activation in breast cancer cells." (PMID 26926077, 2016). "Targeting IGF-1R in sarcoma with radiolabeled antibody and breast cancer with fluorophore-conjugated antibody has been reported." (PMID 26731105, 2016). "Predicted T-helper epitopes, derived from the IGF-1R extracellular and transmembrane domains, induced a significantly greater incidence of Th2 immunity in breast cancer patients as compared to the controls." (PMID 28261624, 2016). "We previously reported that the erbB2 receptor simultaneously interacted with erbB3 and IGF-1R to form a heterotrimeric complex in trastuzumab-resistant breast cancer cells." (PMID 26621843, 2016). "We next investigated the influence of erbB3 receptor and IGF-1R on lapatinib-induced apoptosis in trastuzumab-resistant breast cancer cells." (PMID 26621843, 2016). "In the current study, we demonstrate that IGF1R-KD had minimal effect on mammary tumors that formed by inoculation of the heterogeneous Mvt1 cell line." (PMID 27179633, 2016). "Further research with different types of breast cancer models and different anti-IGF1R strategies are required in order to further determine the feasibility of these results." (PMID 27179633, 2016). "Either IGF-1R kinase inhibitors or siRNA-mediated suppression of IGF-1R expression is sufficient to sensitize breast cancer cells to cisplatin treatment." (PMID 27472395, 2016). "IGF1R is a member of insulin receptor family and it has been shown that in prostate and breast cancer cells AR binds to IGF1R promoter and thus increases IGF1R expression." (PMID 27993167, 2016). "To test the feasibility of our results in CD24+ human breast cancer cells, we downregulated IGF1R in the MCF7 cells and identified a marked reduction in SLPI levels." (PMID 27179633, 2016). "The IGF-1R specific IgG antibodies significantly rise in early-stage breast cancer patients at the time of diagnosis comparing to volunteer donors." (PMID 28261624, 2016). "For long-term analysis of tumour progression following the knockdown of uPAS components and IGF1R with regard to an improved breast cancer therapy, the target proteins were stably downregulated." (PMID 27502396, 2016). "Co-overexpression of uPA, uPAR and IGF1R elevated the malignancy of pancreatic, hepatocellular, rhabdomyosarcoma, colon and breast cancer cells." (PMID 27502396, 2016). "Case control and prospective studies further supported the role of the IGF1R axis in breast cancer patients." (PMID 27179633, 2016).
breast cancer (continued). "To further confirm that compound 2 was capable of altering an IGF-1R signaling network we made use of an 800 gene large signature identified in breast cancer (BC) cells upon IGF-1 treatment." (PMID 27384680, 2016). "The effects of suppressing ATR with siRNA were further tested in the ZR-75-1 ductal breast carcinoma cell line, which was previously shown to be resistant to IGF-1R inhibition (IC50 2μM for BMS-754807)." (PMID 27472395, 2016). "The IGF1R signaling cascade has received increased attention as a potential therapeutic target for breast cancers." (PMID 25749031, 2015). "Contrary to a result from unspecified breast cancer patients, total INSRs and phosphorylated IGF-1R/INSRs overexpression by IHC was related to poor OS in all breast cancer subtypes including those with acquired resistance to tamoxifen." (PMID 26217584, 2015). "Surprisingly, expression of a dominant-negative IGF1R during MMTV-Wnt1-mediated tumorigenesis accelerates mammary tumor formation and promotes aggressiveness." (PMID 25964777, 2015). "Elevated IGF1R levels appear to enhance cell survival and metastasis following chemotherapy, potentially leading to decreased survival for breast cancer patients." (PMID 25749031, 2015). "Upregulation of IGF-1R expression after neoadjuvant treatment is a poor prognostic factor in breast cancer patients, providing a rationale for incorporating anti-IGF-1R drugs in the management of these patients." (PMID 25680198, 2015). "We have previously shown that a chimeric scFv against IGF1R can downregulate IGF1R in breast cancer cells, a general mechanism in antibody resistance." (PMID 26173023, 2015). "Multiple studies have implicated a role for IGF1R in breast cancer, including TNBC, and other malignancies; however, the specific molecular mechanisms underlying IGF1R's involvement in TNBC are not fully understood." (PMID 25749031, 2015). "High ratio of INSR:IGF-1R also conveyed resistance to the IGF-1R mAb cixutumumab in breast cancer cell lines." (PMID 26217584, 2015). "Even though IGF1R influences tumorigenic phenotypes and drug resistance across all breast cancer subtypes, it has specific expression and function in each." (PMID 25964777, 2015). "The growth of Kras expressing murine mammary tumors is delayed upon deletion of the Igf1r gene from mammary tumors." (PMID 25699021, 2015). "FDA-approved drugs targeting HER-1 (gefitinib) and IGF-1R (AG1024) respectively show synergistic therapeutic advantage in in vitro human breast cancer cells, further highlighting the importance of pursuing combination therapies in cancer treatment." (PMID 26350593, 2015). "In models of breast cancer bone metastasis, IGF-1R activation promotes motility of bone-metastatic cells." (PMID 25629807, 2015). "In vitro work by Zhang and colleagues demonstrated that downreguation of the IGF-1R in breast cancer cell line leads to the increased insulin sensitivity." (PMID 26217584, 2015). "The magnitude of Th2 immunity against predicted T-helper epitopes derived from the IGF1R was also greater in breast cancer patients." (PMID 26173023, 2015). "An upregulation of membranous IGF-1R expression after neoadjuvant treatment is a poor prognostic factor in breast cancer patients, providing the rationale for incorporating anti-IGF-1R drugs in the management of this patient group." (PMID 25680198, 2015). "Transgenic overexpression of oncogenic Kras in the murine mammary gland induces the formation of mammary tumors that overexpress Igf1r." (PMID 25699021, 2015). "In this review, we examine IGF1R expression and function as it relates to breast cancer subtype and therapy-acquired resistance." (PMID 25964777, 2015). "For this reason, and following on from several preclinical studies, several trials targeting IGF1R in luminal breast cancer were performed." (PMID 25964777, 2015). "Here we used a panel of MCF7 human breast cancer cell lines that selectively express either one of the isoforms of the INSR or the IGF1R." (PMID 26187749, 2015).
breast cancer (continued). "In this study, we examined the expression of HRD1 in breast cancer and investigated its function in degradation of IGF-1R, in order to better understand its role in tumorigenesis of breast cancer and its potential implications for cancer therapy." (PMID 26536657, 2015). "Overexpression of IGF1R is common in breast carcinomas, and xenograft studies demonstrate that IGF1R up-regulation induces mammary tumor growth and metastases." (PMID 25749031, 2015). "The expression levels of HRD1 in breast cancer patients were significantly correlated with IGF-1R status, breast cancer grade and lymph node metastasis (p < 0.05)." (PMID 26536657, 2015). "Breast cancer cells are thought to have a defect in IGF-1R ubiquitination, which is a necessary step for the degradation of this receptor, but the underlying mechanism is not clearly understood." (PMID 26536657, 2015). "Treating mice with the IGF1R inhibitor picropodophyllin (PPP) suppressed the growth of Kras expressing mammary tumors compared with vehicle." (PMID 25699021, 2015). "Another approach to establish the function of IGF-1R in different types of breast cancers is to disrupt IGF-1R in mouse tumor models with distinct phenotypes." (PMID 26106366, 2015). "This role for IGF1R in promotion of stem-like characteristics has been specifically demonstrated in primary breast cancer." (PMID 25964777, 2015). "The cross talk between ER-α, ER-β and IGF-1R exists such that breast cancer cell lines with suppressed IGF-1R expression showed low level of ER-α but high level of ER-β27." (PMID 26492952, 2015). "Below, we describe the main breast cancer molecular subtypes and the role IGF1R is believed to play in each." (PMID 25964777, 2015). "Insulin-like growth factor Type-1 receptor (IGF1R) is frequently overexpressed in primary human breast cancers, with a growing role in the TN phenotype." (PMID 26449867, 2015). "Subsequent studies in breast cancer examining high HR:IGF-1R demonstrated greater anti-tumoral activity using h7C10, a mAb targeting HR and IGF-1R, compared to mAbs targeting IGF-1R alone." (PMID 26217584, 2015). "In vitro experiments treating breast cancer cell lines overexpressing HRs with IGF-1 induced greater auto-phosphorylation compared to IGF-1R homodimers." (PMID 26217584, 2015). "The studies establishing the IGF-1R as growth promoting for breast cancers suggests some complexity concerning IGF-1R function in breast cancers." (PMID 26106366, 2015). "The data presented in this manuscript suggests an interaction between the two pathways, as demonstrated by the enhanced protein levels of IGF-1R, p-IGF-1R, p-IRS-1, p-AKT and p-S6 in ovarian and breast cancer cells having loss-of-function mutations of BRCA1." (PMID 26510816, 2015). "Overall, only IR, IGF1R, p-Erk or p-Akt levels were significantly affected in insulin analogue treatment-related mammary tumor." (PMID 25848982, 2015). "In non-small cell lung carcinoma, miR-140 suppresses tumor growth and metastasis by downregulating IGF1R, and in breast cancer, miR-140 targets Sox2." (PMID 25978641, 2015). "Nevertheless, inhibiting of IGF-1R expression and enhancing its degradation is considered as a promising potential therapeutic strategy for the treatment of breast cancer." (PMID 26536657, 2015). "The molecular link between PDZK1 and IGF-1R was supported by a significant correlation between protein and mRNA levels of the two factors in two independent cohorts of human breast cancer tissues." (PMID 26183824, 2015). "Collectively, these reports provided in vitro and in vivo evidence that the IGF1R promotes transformation and the progression of breast cancer." (PMID 25699021, 2015). "A monoclonal antibody R1507, labeled with 111In or 89Zr, was found to allow imaging of IGF-1R-expressing SUM149 breast cancer xenografts in mice." (PMID 25425114, 2015). "IGF1R expression was assessed by immunohistochemistry (IHC) using a similar scoring system as for HER2 in breast cancer." (PMID 26449867, 2015).
breast cancer (continued). "In human breast cancer, few studies take into account both membrane and cytoplasmic IGF1R expression." (PMID 26449867, 2015). "Taken together, these studies in childhood sarcomas, and prostate, and breast cancers suggest that more studies are needed to investigate the potential of components outside the IGF axis to provide valuable predictive biomarkers for IGF-1R inhibition." (PMID 26217584, 2015). "Anti-IGF-1R mAbs have demonstrated potent growth inhibition in breast cancer cell lines with a low HR:IGF-1R ratio." (PMID 26217584, 2015). "In human primary breast cancer xenografts, total and phosphorylated IGF1R expression is significantly higher in the CD44+CD24− sorted breast cancer stem cell population compared to the non-CD44+CD24− population." (PMID 25964777, 2015). "Toward this goal, we have in this study investigated a new probe, 99mTc-ZIGF1R:4551-GGGC, for determining the level of IGF-1R expression by radionuclide molecular imaging in pre-clinical models of prostate and breast cancer." (PMID 25425114, 2015). "The purpose of this study was to investigate the Dog as a candidate model for IGF1R-overexpressing mammary carcinoma." (PMID 26449867, 2015). "In fact, IGF1R amplification has been reported in malignant melanomas, breast cancers, pancreatic adenocarcinomas, gastric cell lines, rhabdomyosarcomas, Wilms' tumors, and gastrointestinal stromal tumors." (PMID 25110710, 2014). "Taken together, our findings suggest miR-630 as a key regulator of cancer cell progression in HER2 over-expressing breast cancer, through targeting of IGF1R." (PMID 24655723, 2014). "In breast cancer, it is evident that IGF1R is involved in resistance to endocrine therapy, anti-human epidermal growth factor receptor 2 (Her2) therapy and chemotherapy." (PMID 24392142, 2014). "In brief, together with the anti-proliferation effect of calycosin against breast cancer cells, we here explored the role of ERβ-mediated IGF-1R pathway in ER-positive cells, so as to better define the molecular mechanism of calycosin functions." (PMID 24618835, 2014). "The IGF pathway and its receptor component IGF1R appears to play important roles in breast cancer progression and tumor growth." (PMID 24392142, 2014). "Restoring cellular miR-375 level suppresses trastuzumab resistance of breast cancers by directly targeting the insulin-like growth factor 1 receptor (IGF1R)." (PMID 24571711, 2014). "Breast cancer is a heterogeneous disease with different tumor subtypes, we focused on the effect of IGF1R in a mixed population of Korean women with mixed status of ER, PR, HER, and triple negative tumor subtypes." (PMID 24392142, 2014). "The aim of this study was to investigate if IGF1R and its downstream pathway was activated or deregulated in primary breast cancer and to explore if any of the markers were prognostic, with or without adjuvant tamoxifen." (PMID 25362932, 2014). "Recently, it has been shown that methylsulfonylmethane (MSM), a natural compound without any known toxicities, effectively inhibits the STAT3/VEGF and STAT5B/insulin-like growth factor receptor (IGF-1R) pathways in human breast cancer cells." (PMID 24913037, 2014). "The underlying mechanisms for these results need further investigation in order to elucidate the role of IGF1R in the development of resistance against endocrine therapy in breast cancer." (PMID 25362932, 2014). "In clinical breast cancer samples, miR-375 expression was inversely correlated with IGF1R mRNA levels (p = 0.0299)." (PMID 24571711, 2014). "Recent studies have demonstrated that aberrant expression of IGF-1R was correlated with tumor growth and poor prognosis in several human cancers such as myeloma and breast cancer." (PMID 24810113, 2014). "Early clinical trials employing monoclonal antibodies against IGF1R are currently underway in a variety of solid tumors including breast cancer." (PMID 24637962, 2014).